CRTC3 (CREB regulated transcription coactivator 3)
Description:
Transcriptional coactivator for CREB1 which activates transcription through both consensus and variant cAMP response element (CRE) sites. Acts as a coactivator, in the SIK/TORC signaling pathway, being active when dephosphorylated and acts independently of CREB1 'Ser-133' phosphorylation. Enhances the interaction of CREB1 with TAF4. Regulates the expression of specific CREB-activated genes such as the steroidogenic gene, StAR. Potent coactivator of PPARGC1A and inducer of mitochondrial biogenesis in muscle cells. Also coactivator for TAX activation of the human T-cell leukemia virus type 1 (HTLV-1) long terminal repeats (LTR).
Synonyms: TORC-3; TORC3; FLJ21868
Tractability: PROTAC: UniProt records ubiquitination sites on it; ubiquitination databases record sites on it; its protein half-life has been measured.
Gene: Protein-coding gene on chromosome 15 (90,529,890 to 90,645,345, forward strand). Ensembl gene ENSG00000140577.
Subcellular location: Nucleus; Cytoplasm
Subcellular location (Human Protein Atlas): Nucleoplasm; Cytosol
Pathways (Reactome):
Cellular responses to stimuli: Heme signaling
Circadian clock: Expression of BMAL (ARNTL), CLOCK, and NPAS2
Organelle biogenesis and maintenance: Transcriptional activation of mitochondrial biogenesis
Gene Ontology:
Molecular function: protein binding; cAMP response element binding protein binding; transcription coactivator activity
Biological process: macrophage activation; cellular response to cAMP; negative regulation of adenylate cyclase-activating adrenergic receptor signaling pathway; positive regulation of transcription by RNA polymerase II; protein homotetramerization
Cellular component: cytoplasm; cytosol; nucleoplasm; nucleus
Genetic constraint (gnomAD): Loss-of-function variants: 16 observed, 44.66 expected, observed/expected ratio (o/e) 0.36, 90% interval 0.24 to 0.54. The synonymous counts are far from expectation, so gnomAD's model fits this gene poorly and the ratio says little. Missense variants: 608 observed, 610.43 expected, observed/expected ratio (o/e) 1, 90% interval 0.93 to 1.07. Synonymous variants: 314 observed, 258.86 expected, observed/expected ratio (o/e) 1.21, 90% interval 1.11 to 1.33.
Homologues: Orthologues: chimpanzee CRTC3 (99% identical), macaque CRTC3 (99% identical), pig CRTC3 (92% identical), dog CRTC3 (90% identical), mouse Crtc3 (89% identical), rabbit CRTC3 (88% identical), rat Crtc3 (88% identical), guinea pig CRTC3 (87% identical), tropical clawed frog crtc3 (56% identical), zebrafish crtc3 (38% identical), Drosophila melanogaster Crtc (22% identical), Caenorhabditis elegans crtc-1 (16% identical). Paralogues in human: CRTC2 (39% identical), CRTC1 (35% identical).
Diseases named in the same sentence as CRTC3 in open-access papers:
CRTC3 is named in the same sentence as 30 diseases in open-access papers, as found by Europe PMC text mining. Sharing a sentence is not in itself a finding about the gene and the disease. The quoted sentences say what the papers report.
Obesity (10 papers, 2015 to 2023). Accumulation of substantial excess body fat. "CRTC3 plays important roles in regulating energy metabolism and the expression of genes associated with fat deposition and obesity." (PMID 33653408, 2021). "For example, several studies showed that the CRTC3, a commonly upregulated gene in Wilson’s disease HLCs of this study, is linked with obesity and hepatic steatosis." (PMID 32252475, 2020). "In adipocytes, CRTC3 plays a major role in lipid metabolism, with CRTC3 polymorphisms being associated with obesity." (PMID 30021947, 2018). "Previous studies demonstrated that CRTC3 is expressed at high levels in adipose tissues from different locations, and its expression is linked to skeletal muscle fat deposition, obesity and energy metabolism." (PMID 33653408, 2021). "Song reported that CRTC3 promotes obesity by attenuating sympathetic signaling and suppressing fatty acid oxidation in adipose tissues." (PMID 37666810, 2023). "Studies should investigate whether CRTC3 expressions or the degree of obesity correlates with treatment efficacies of ICIs or sorafenib in HCC." (PMID 37666810, 2023). "The global deletion of CRTC3 enhances energy expenditure and protects mutant mice from obesity." (PMID 33653408, 2021). "In addition, CRTC3 overexpression altered the levels of tricarboxylic acid (TCA) cycle intermediates, including fumarate, citrate and malate, and the concentrations of these intermediates are positively associated with obesity." (PMID 33653408, 2021). "It is also of great importance to test whether Ro31-8220 application can be extended to metabolic syndrome treatment since adipose tissue CRTC3 contributes to energy metabolism and genetic ablation of CRTC3 in mice improves diabetes and obesity phenotypes 8, 29-32." (PMID 32226536, 2020). "CRTC3 is most prominently expressed in white adipose tissue (WAT) and promotes obesity." (PMID 27869139, 2016).
melanoma (3 papers, 2021 to 2023). A malignant, usually aggressive tumor composed of atypical, neoplastic melanocytes. "Only a few reports showed that CRTC3 promoted melanogenesis by regulating the expression of some key melanogenesis-related genes in melanoma." (PMID 37666810, 2023). "A recent study describing CRTC3-null mice 43 and CRTC3 function in melanocyte differentiation and melanoma oncogenesis reported coat color phenotypes similar to those observed in our study." (PMID 34815795, 2021).
lung carcinoma (2 papers, 2021). "Endogenous CRTC1, CRTC2, and CRTC3 proteins showed slow migration patterns in LKB1-expressing lung cancer cells (H322)." (PMID 34142658, 2021).
acute coronary syndrome (1 paper, 2018). Signs and symptoms related to acute ischemia of the myocardium secondary to coronary artery disease. "In conclusion, CRTC3 polymorphism was associated with the onset of acute coronary syndrome in Han Chinese." (PMID 29979427, 2018). "Despite the fact that we proved CRTC3 polymorphism was associated with the onset of acute coronary syndrome in Han Chinese patients, we cannot find the exact mechanism for it up to now." (PMID 29979427, 2018). "CRTC3 polymorphism was associated with the onset of acute coronary syndrome in Han Chinese patients, which may be related to the imbalance of the lipid metabolism." (PMID 29979427, 2018). "In the present study, we investigate the SNP of CRTC3, rs3862434, and rs11635252 in patients with acute coronary syndrome (ACS)." (PMID 29979427, 2018).
Anxiety (1 paper, 2020). Intense feelings of nervousness, tension, or panic often arise in response to interpersonal stresses. "The MAPK pathway has been associated with OT-induced anxiolysis, i.e., reduction of anxiety-like behavior in rats and targets transcription factors such as CREB and its cofactor CRTC3." (PMID 32209973, 2020).
Hashimoto thyroiditis (1 paper, 2025). An autoimmune disorder caused by the production of autoantibodies against thyroid tissue. "In contrast to thyroid SMECE which is a distinct entity arising in the background of fibrosing Hashimoto thyroiditis and lacking MAML2 gene alterations, salivary SMEC is a rare variant of MEC characterized by MAML2 gene break and/or CTRC1/CRTC3::MAML2 gene fusion." (PMID 39537991, 2025).
hepatocellular carcinoma (1 paper, 2023). A malignant tumor that arises from hepatocytes. "Analysis of CRTC3 mRNA levels using The Cancer Genome Atlas Liver Hepatocellular Carcinoma (TCGA‐LIHC) database revealed that HCC tissues exhibited significantly higher mRNA levels of CRTC3, compared to normal tissues." (PMID 37666810, 2023).
microphthalmia (1 paper, 2021). Congenital or developmental anomaly in which the eyeballs are abnormally small. "Regarding the central role of MITF in melanocyte lineage development, the ocular structure of CRTC3-null mice was comparable to the control mice with respect to microphthalmia or decoloration." (PMID 34815795, 2021).
mucoepidermoid carcinoma (1 paper, 2024). A carcinoma morphologically characterized the presence of cuboidal mucous cells, goblet-like mucous cells, squamoid cells, cystic changes, and a fibrotic stromal formation. "These include fusions of the ETV6 gene in secretory carcinoma (SC), MYB/MYBL1::NFIB in adenoid cystic carcinoma (AdCC), CRTC1/CRTC3::MAML2 in mucoepidermoid carcinoma (MEC), and EWSR1::ATF1 in hyalinizing clear cell carcinoma as the most frequent and best characterized gene fusions." (PMID 38217715, 2024).
ovarian carcinoma (1 paper, 2025). A malignant neoplasm originating from the surface ovarian epithelium. "CRTC3 promotes melanocyte differentiation and tumorigenesis by integrating cAMP and MAPK/ERK signaling, while CRTC2 enhances autophagic flux via PI3K-AKT pathway activation, reducing paclitaxel sensitivity in ovarian cancer cells." (PMID 40977688, 2025).
schizophrenia (1 paper, 2023). A major psychotic disorder characterized by abnormalities in the perception or expression of reality. "CRTC3 was recently reported to be related to treatment-resistant depression in genome-wide association study and also as a genetic variant associated with autism spectrum disorders and schizophrenia." (PMID 37730843, 2023).
type 2 diabetes mellitus (1 paper, 2021). A type of diabetes mellitus that is characterized by insulin resistance or desensitization and increased blood glucose levels. "Our heatmap results showed that CRTC3 overexpression significantly increased the expression of genes related to the risk of type II diabetes mellitus in CRTC3-overexpressing adipocytes." (PMID 33653408, 2021). "KEGG pathway analysis showed that CRTC3 overexpression also upregulated genes that were involved in calcium signaling, estrogen signaling pathways, type II diabetes mellitus, and cytokine-cytokine receptor interaction signaling pathways." (PMID 33653408, 2021).
Wilson disease (1 paper, 2020). A very rare inherited multisystemic disease presenting non-specific neurological, hepatic, psychiatric or osseo-muscular manifestations due to excessive copper deposition in the body. "Because the fat accumulation is frequently observed in the liver of Wilson’s disease patients, targeting CRTC3 possibly provides a new concurrent treatment with existing medications (e.g., copper chelators) for Wilson’s disease patients." (PMID 32252475, 2020).
cancer (5 papers, 2018 to 2023). A tumor composed of atypical neoplastic, often pleomorphic cells that invade other tissues. "Our findings elucidate a novel role of CRTC3 in regulating ferroptotic cell death, and presented a potential target of the CRTC3 pathway for cancer treatment." (PMID 37666810, 2023). "We knocked down CRTC3 which was a downstream factor of SIKs in L929 cells, which played various roles in cancer and inflammation." (PMID 35217652, 2022). "Three members of the CRTC co-activator family, CRTC1, CRTC2, and CRTC3, are expressed at varying levels in human lung epithelial and cancer cell lines." (PMID 34142658, 2021). "The CRTC family consists of three members, CRTC1, CRTC2, and CRTC3, which play important roles in metabolism, aging, and cancer." (PMID 34142658, 2021). "However, the mobility of CRTC3 appeared relatively unchanged in 4/6 LKB1-null cancer cell lines, suggesting a distinct pattern of post-translational regulation." (PMID 34142658, 2021). "We were not able to validate the association of STAG2- and CRTC3-related signatures with survival in ER-positive/HER2-negative cancers due to the lack of the probe sets specific for these signatures in the Illumina gene chips." (PMID 29559730, 2018).
tumor (3 papers, 2018 to 2023). "Tumor growths in CRTC3-KO cell-bearing mice were significantly inhibited by sorafenib treatment, compared to the vehicle." (PMID 37666810, 2023). "Immunohistochemistry (IHC) analyses of tumor tissues confirmed that CRTC3 knockout enhanced the expressions of GPx4 in vivo." (PMID 37666810, 2023). "We found that CRTC3 knockout sensitized HCC cells to sorafenib by reprograming tumor cell lipid metabolism and facilitating ferroptosis, which provides a new clue for optimizing sorafenib treatment." (PMID 37666810, 2023). "For the first time, we reported that CRTC3 regulates ferroptosis by altering tumor cell lipid patterns and controlling the abundance of PUFAs in HCC." (PMID 37666810, 2023). "By analyzing the TCGA‐LIHC database, we found that tumor tissues exhibited significantly higher CRTC3 mRNA levels." (PMID 37666810, 2023). "Mechanistically, CRTC3 knockout altered tumor cell lipid patterns and increased the abundance of polyunsaturated fatty acids (PUFAs), which enables lipid peroxidation and enhances the susceptibility of HCC cells to ferroptosis inducers." (PMID 37666810, 2023). "Evaluation of sensitizing effects of CRTC3 depletion to sorafenib treatment revealed significantly enhanced anti-tumor effects in CRTC3-KO HCC cells, which were separately rescued by Ferrostatin-1 and PRGL493 treatments." (PMID 37666810, 2023). "CRTC3 expression in tumor tissues might protect tumor cells from ferroptosis and result in drug resistance." (PMID 37666810, 2023). "Since IFN-γ was reported to induce apoptosis in tumor cells, we further performed Caspase 3/7 assay to verify whether CRTC3 knockout sensitized HCC cells to treatment by inducing apoptosis." (PMID 37666810, 2023). "CRTC3 had no significant impact on tumor growth in HCC cells both in vitro and in vivo." (PMID 37666810, 2023).
infection (1 paper, 2018). The state of being infected such as from the introduction of a foreign agent such as serum, vaccine, antigenic substance or organism. "Infection of VSMC with Ad:CRTC2S171A or Ad:CRTC3S161A resulted in equal expression of FLAG-tagged CRTC2 and CRTC3 protein and a significant increase in CREB activity." (PMID 29559698, 2018).
skin disorder (1 paper, 2021). Any deviation from the normal structure or function of the skin or subcutaneous tissue that is manifested by a characteristic set of symptoms and signs. "In conclusion, understanding the detailed molecular mechanisms of epidermal pigmentation by CRTC3 modulation could lead to the development of new strategies to protect against UVB-induced skin carcinogenesis and treat hyper- or hypo-pigmentation skin disorders." (PMID 34815795, 2021).
CRTC3 also shares sentences with these, for which no sentence is quoted: Hepatic steatosis (2 papers); adenoma (1); alopecia (1); autism (1); colorectal cancer (1); depression (1); diabetes (1); mandibulofacial dysostosis (1); melasma (1); mental disorder (1); metabolic syndrome (1); salivary gland tumours (1); thyroid (1).